ENO4 (enolase 4)
Description:
Enolase that catalyzes the conversion of 2-phosphoglycerate to phosphoenolpyruvate in glycolysis and the reverse reaction in gluconeogenesis (By similarity). May be required for sperm motility and function.
Synonyms: C10orf134; AC023283.3; ENOS
Tractability: No criterion of Open Targets' tractability assessment is met for any kind of drug.
Gene: Protein-coding gene on chromosome 10 (116,849,481 to 116,911,788, forward strand). Ensembl gene ENSG00000188316.
Subcellular location (Human Protein Atlas): Vesicles; Cytosol
Pathways (Reactome):
Metabolism: Gluconeogenesis; Glycolysis
Gene Ontology:
Molecular function: phosphopyruvate hydratase activity; magnesium ion binding
Biological process: glycolytic process
Cellular component: phosphopyruvate hydratase complex
Genetic constraint (gnomAD): Loss-of-function variants: 33 observed, 49.72 expected, observed/expected ratio (o/e) 0.66, 90% interval 0.5 to 0.89. The upper end of that interval is the gene's LOEUF score, 0.89, which puts it in group 3 of 6, group 1 being the genes least tolerant of losing a copy. Missense variants: 646 observed, 699.25 expected, observed/expected ratio (o/e) 0.92, 90% interval 0.87 to 0.99. Synonymous variants: 249 observed, 259.02 expected, observed/expected ratio (o/e) 0.96, 90% interval 0.87 to 1.07.
Homologues: Orthologues: chimpanzee ENO4 (99% identical), macaque ENO4 (96% identical), pig ENO4 (83% identical), dog ENO4 (80% identical), rabbit ENO4 (79% identical), guinea pig ENO4 (78% identical), mouse Eno4 (72% identical), rat Eno4 (72% identical), tropical clawed frog eno4 (46% identical), zebrafish eno4 (36% identical), Caenorhabditis elegans enol-1 (19% identical), Drosophila melanogaster Eno (18% identical). Paralogues in human: ENO2 (18% identical), ENO3 (18% identical), ENO1 (17% identical).
Diseases named in the same sentence as ENO4 in open-access papers:
ENO4 is named in the same sentence as 8 diseases in open-access papers, as found by Europe PMC text mining. Sharing a sentence is not in itself a finding about the gene and the disease. The quoted sentences say what the papers report.
depression (2 papers, 2024). "Two (14%) of the 14 total disrupted glycolytic genes were downregulated: ENO4 and PGK2, and their expression was 2.4× lower in depression groups compared to control groups (LFC = −1.19)." (PMID 39125835, 2024).
Hydrocephalus (1 paper, 2020). Hydrocephalus is an active distension of the ventricular system of the brain resulting from inadequate passage of CSF from its point of production within the cerebral ventricles to its point of absorption into the systemic circulation. "Interestingly, although Eno4 KO mice exhibited severe malformations of the spermatids of the cauda epididymis, only minor abnormalities were apparent in the histology and ultrastructure of the testis, with no indication of hydrocephalus." (PMID 32248064, 2020).
ENO4 also shares sentences with these, for which no sentence is quoted: male infertility (3 papers); Infertility (2); female infertility (1); ovarian insufficiency (1); schizophrenia (1); tumours (1).